CTSS (cathepsin S)
Diseases named in the same sentence as CTSS in open-access papers (continued):
Sharing a sentence is not in itself a finding about the gene and the disease.
osteoarthritis (3 papers, 2012 to 2020). A noninflammatory degenerative joint disease occurring chiefly in older persons, characterized by degeneration of the articular cartilage, hypertrophy of bone at the margins and changes in the synovial membrane. "Moreover, the expression of several key features of osteoarthritis pathology and pro-inflammatory mediators (e.g. cysteine proteases cathepsin S and cathepsin C), were detected among the highly regulated genes during DN-Erg chondrocyte culture." (PMID 23155398, 2012).
osteoporosis (3 papers, 2016 to 2020). A condition of reduced bone mass, with decreased cortical thickness and a decrease in the number and size of the trabeculae of cancellous bone (but normal chemical composition), resulting in increased fracture incidence. "CTSK inhibitors have been proved successful improving osteoporosis; however, concerns emerged over off-target effects of the inhibitors against other CTSs and CTSK inhibition at nonbone sites (i.e., skin, and cardiovascular and cerebrovascular sites)." (PMID 32326609, 2020).
pancreatic islet cancer (3 papers, 2011 to 2023). "This has been demonstrated previously in a RIP1-Tag2 murine pancreatic islet cancer model, wherein, knocking out CTSS led to a reduction in invasion, as a result of a diminution in E-cadherin cleavage." (PMID 38116078, 2023).
papillary thyroid cancer (3 papers, 2020 to 2025). "Previous articles in papillary thyroid carcinoma reported that CTSS was highly expressed and related to transformation." (PMID 34266404, 2021). "High expression of CTSS is a predictor of poor prognosis and tumor metastasis in papillary carcinoma of the thyroid." (PMID 33240321, 2020).
peripheral nerve injury (3 papers, 2015 to 2021). Injury to a peripheral nerve. "Cathepsin S-mediated Cx3cl1 secretion seems to be crucial for the development of neuropathic pain, because inhibition of cathepsin S activity facilitates pain control in a peripheral nerve injury model." (PMID 34944440, 2021).
pulmonary arterial hypertension (3 papers, 2015 to 2024). Pulmonary arterial hypertension (PAH) is a group of diseases characterized by mean pulmonary artery pressure >20 mmHg and elevated pulmonary arterial resistance leading to right heart failure. "Ctss is a potent protease cleaving elastin in the arterial wall, and upregulation of CTSS has been observed in lung tissue from human patients with pulmonary arterial hypertension." (PMID 37660920, 2023).
renal cell carcinoma (3 papers, 2019 to 2026). "Fisetin inhibited the migration as well as the invasion of human renal cell carcinoma (RCC) cells via the downregulation of CTSS and MMP-9 (ADAM9) and disintegrin." (PMID 36558146, 2022).
schizophrenia (3 papers, 2020 to 2024). A major psychotic disorder characterized by abnormalities in the perception or expression of reality. "Recent genetic studies have found potential associations between the CTSS gene and susceptibility to schizophrenia." (PMID 38637810, 2024). "Research highlights Cathepsin S's involvement in memory function in the brain and its association with psychiatric disorders such as MDD, bipolar affective disorder, and schizophrenia." (PMID 38637810, 2024). "Based on this, three-step SMR and colocalization analyses identified ITIH3 and CCS as being related to the risk of developing depression, while CTSS and DNPH1 are related to the onset of schizophrenia." (PMID 38637810, 2024). "Additionally, tissue proteinase S (CTSS) is renowned for its involvement in protein degradation and maintenance of blood–brain barrier integrity, suggesting potential connections with schizophrenia." (PMID 38637810, 2024). "Through coloc analysis, ITIH3 was conclusively associated with the onset of depression, CCS exhibited associations with depression at both the gene and protein levels, and CTSS and DNPH1 were implicated in the onset of schizophrenia at both the gene and protein levels." (PMID 38637810, 2024). "A total of three such sites were identified: CCS for depression and CTSS and DNPH1 for schizophrenia." (PMID 38637810, 2024). "The pQTL‐protein pairs CTSS‐rs79671334 and RARRES2‐rs3735172 had shared effects with schizophrenia and year of schooling, respectively." (PMID 36504281, 2023). "In addition, disrupted PNN rhythm composition by cathepsin-S in expression from microglia in subjects with schizophrenia may contribute to memory consolidation deficits through disruption of local synaptic downscaling and reorganization proposed to occur during sleep." (PMID 32719104, 2020).
type 1 diabetes (3 papers, 2017 to 2025). "The lysosomal protease cathepsin S (Ctss) has previously been associated with type 1 diabetes." (PMID 39595046, 2024).
ulcerative colitis (3 papers, 2024 to 2025). An inflammatory bowel disease involving the mucosal surface of the large intestine and rectum. "We observed a significant increase in fecal cathepsin S in patients with ulcerative colitis compared to healthy controls, while cathepsin S in mucosal biopsies was unchanged." (PMID 41436824, 2025). "To determine whether cathepsin S is activated in the colons of patients with ulcerative colitis, we applied a fluorescently quenched activity-based probe (ABP), BMV15720." (PMID 41436824, 2025). "Although BMV157 labeling was clearly detected across both pH, we did not observe any statistically significant differences in cathepsin S activity between healthy volunteers and patients with ulcerative colitis." (PMID 41436824, 2025).
acute coronary syndrome (2 papers, 2021 to 2025). Signs and symptoms related to acute ischemia of the myocardium secondary to coronary artery disease. "Patients with acute coronary syndrome (ACS) had substantially higher levels of serum cathepsin S than those with stable angina pectoris (SAP), with the median 34.65 ng/ml (24.33–42.83) and 25.52 ng/ml (20.53–31.47), respectively (P < 0.01)." (PMID 33746900, 2021). "Moreover, patients with acute coronary syndrome (ACS) had substantially higher levels of serum cathepsin S than those with stable angina pectoris (SAP), with the median 34.65 ng/ml (24.33–42.83) and 25.52 ng/ml (20.53–31.47) respectively (P < 0.01)." (PMID 33746900, 2021). "Notably, studies on amyloid beta and cathepsin S used ELISA and focused on patients with non-ST elevation acute coronary syndrome." (PMID 39445733, 2025).
Anxiety (2 papers, 2020 to 2025). Intense feelings of nervousness, tension, or panic often arise in response to interpersonal stresses. "Moreover, the mice in the CTSS knockdown group did not exhibit anxiety‐like behaviors, reflected by the equal time spent in centers compared to those in the control group." (PMID 39453382, 2025).
brain injury (2 papers, 2018 to 2022). Acute and chronic (see also brain INJURIES, CHRONIC) injuries to the brain, including the cerebral hemispheres, CEREBELLUM, and brain STEM. "It is also involved in secondary brain damage following traumatic brain injury, where inhibition of cathepsin S had beneficial effects on rescuing brain damage and improving neurobehavioral recovery." (PMID 29452862, 2018). "Cathepsin S (CTSS) is mainly produced by microglia in the hippocampi of kainate-injected mice, and prohibition of its function resulted in reducing inflammation and alleviating brain edema in a mouse model of traumatic brain injury." (PMID 36531133, 2022).
brain tumor (2 papers, 2012 to 2021). "Microdialysis, an extracellular fluid sampling approach originally designed to collect neurotransmitters, confirmed that cathepsin S was present in the extracellular space of brain tumors." (PMID 34572924, 2021). "Human cancers, including prostate, gastrointestinal (gastric, colorectal), lung, and brain tumors (astrocytoma, glioblastoma) upregulate cathepsin S." (PMID 34572924, 2021).
Cerebral ischemia (2 papers, 2024 to 2025). Restriction of arterial blood supply to the brain associated with insufficient oxygenation to support the metabolic requirements of the tissue. "Importantly, a recent study identified that monocytes with high cathepsin S expression aggravated cerebral ischemia–reperfusion injury via promoting blood-brain barrier destruction through junctional protein cleavage." (PMID 40115073, 2025). "In addition, five proteins are shown to bind to neuroinflammation and cerebral ischemia, including parvalbumin alpha, superoxide dismutase, S‐adenosyl‐l‐homocysteine hydrolase, 3‐mercaptopyruvate sulfurtransferase, and cathepsin S." (PMID 38376040, 2024).
Chagas disease (2 papers, 2019 to 2025). A parasitic infection caused by Trypanosoma cruzi. "Remarkably, it has been demonstrated that CD4+ T-cells from Chagas disease patients possess the ability to proliferate when exposed to the P214-cruzipan epitope, which exhibits structural similarity to the catalytic domain of cathepsin S." (PMID 40391216, 2025).
cognitive decline (2 papers, 2025). "In aging and AD model mice, the expression level of neuronal CTSS is significantly elevated in neurons, which increases neuroinflammation and causes cognitive decline via CX3CL1‐CX3CR1 axis and JAK2‐STAT3 pathway." (PMID 39453382, 2025).
Cognitive impairment (2 papers, 2022 to 2024). Abnormal cognition is characterized by deficits in thinking, reasoning, or remembering. "This suggests that suppressing CTSS could be a potential therapeutic target to ameliorate cognitive impairment." (PMID 38725007, 2024). "In a proteomic analysis, NCAN, BCAN, CTSS, MSR1, MDGA1, and CPA2 were reported as upregulated in individuals with PTSD and comorbid mild cognitive impairment." (PMID 35625844, 2022).
colon adenocarcinoma (2 papers, 2016 to 2025). "In the TCGA colon adenocarcinoma dataset, CTSS expression was significantly negatively correlated with tumor purity (Rho = − 0.172, P = 0.0005) and significantly positively correlated with regulatory T-cells (Rho = 0.45, P = 4.13 × 10−15) and M2 macrophages (Rho = 0.426, P = 1.41 × 10−13)." (PMID 40794185, 2025).
coronary atherosclerosis (2 papers, 2018 to 2023). Atherosclerosis of the coronary vasculature. "In coronary atherosclerosis, cathepsin S (CTSS) transcripts contain inverted Alu repeat sequence regions, and edited Alu dsRNA disrupts the structure of dsRNA, and ADAR1 recruits the RNA-binding protein HuR, thereby increasing the stability of CTSS mRNA." (PMID 37328893, 2023). "Clinical studies showed that the level of CTSS is positively related with the degree of coronary atherosclerosis." (PMID 30341237, 2018).
cutaneous melanoma (2 papers, 2020 to 2022). A primary melanoma arising from atypical melanocytes in the skin. "The clinical relevance of these results is demonstrated by the fact that in human cutaneous melanoma biopsies, IL-BCG therapy was associated with enhanced M1 MΦ, mature DC, antigen processing and presentation, as well as with elevated CTSS expression." (PMID 35732347, 2022).
E. coli (2 papers, 2020 to 2023). "Further qRT-PCR assays showed that representative genes of phagosome maturation were significantly upregulated in response to E. coli infection including ATP6V1A, ATP6V1B2, BF2, CTSS, and TFRC, while COLEC12 was downregulated at 72 h." (PMID 36411420, 2023).
fibrosarcoma (2 papers, 2019 to 2025). A malignant mesenchymal fibroblastic neoplasm affecting the soft tissue and bone. "In BC, the expression of cathepsin S (CTSS), a protease involved in tumor angiogenesis, is regulated by the PI3K/AKT and rat sarcoma virus oncogene (Ras)/rapidly accelerated fibrosarcoma (Raf)/MAPK pathways." (PMID 41415714, 2025).
fibrosis (2 papers, 2022). the formation of excess fibrous connective tissue in an organ or tissue in a reparative or reactive process. "Therefore, cathepsin S, PAR2, and ZEB1 regulate intestinal fibrosis development in mice." (PMID 35840034, 2022).
Hodgkins lymphoma (2 papers, 2022 to 2024). A heterogeneous group of malignant lymphoid neoplasms of B-cell origin characterized histologically by the presence of Hodgkin and Reed-Sternberg (HRS) cells in the vast majority of cases. "In our study, genes related to major histocompatibility complex (MHC) class I and II machinery/biosynthesis such as HLA-DRA, CTSS, HLA-DPA1, HLA-DPB1, CTSC, B2M genes were expressed at higher levels in the mixed-cellularity subtype than in nodular sclerosis subtype at diagnosis." (PMID 36230815, 2022).
hydronephrosis (2 papers, 2020 to 2021). Collection of urine in the renal pelvis that results in dilatation of the renal pelvis and calyces. "CTSS was also shown to affect epithelial-to-mesenchymal transition and ECM deposition in mouse models of mild and severe hydronephrosis, indicating its role in the regulation of renal fibrosis." (PMID 34376786, 2021).
lymph node metastasis (2 papers, 2021 to 2025). "Employing comprehensive bioinformatics analysis, they suggested that Cathepsin S was an independent risk factor for poor disease-free survival and that high expression of Cathepsin S was independently linked with lymph node metastasis." (PMID 39791166, 2025). "In their study, Juan Tan and associates found that the expression of Cathepsin S correlated with lymph node metastasis and adverse outcomes in papillary thyroid carcinoma." (PMID 39791166, 2025).
mental disorder (2 papers, 2024 to 2025). A disease that has its basis in the disruption of mental process. "Cathepsin S also plays a role in regulating the integrity of the blood–brain barrier (BBB), and changes in BBB permeability may affect the entry of immune cells and inflammatory factors into the brain, potentially contributing to the onset of psychiatric disorders." (PMID 38637810, 2024).
nasopharyngeal carcinoma (2 papers, 2015 to 2016). A carcinoma arising from the nasopharyngeal epithelium. "In addition, when Cathepsin S (CTSS) was inhibited, autophagy and intracellular ROS were induced in HONE1 nasopharyngeal carcinoma cells." (PMID 26416514, 2015).
neuropathic pain (2 papers, 2014 to 2016). Chronic pain caused by damage to nerve fibers. "Microglial MAP kinases can be activated by IL-1β and TNF-α, inducing, via transcription factors such as NFκB, additional production of IL-1β, TNF-α, IL-6, IL-10, TGF-β, PGE2, BDNF, and cathepsin S and promoting the deleterious effects of microglial infiltration and phagocytosis in neuropathic pain." (PMID 24642655, 2014). "Of the 47 investigated proteins, 21 (cathepsin S, CCL2, CCL4, CCL16, CFIII, CXCL5, cystatin B, E-Selectin, Fas/TNFRSF6, follistatin, GDF-15, GH, ICAM1, IL8, KLK5, MMP2, MMP9, P-Selectin, sortilin, TIMP4 and VEGF) were detectable by multiplex SP-PLA in ≥ 95% of the neuropathic pain patient samples." (PMID 26914813, 2016).
non-small cell lung carcinoma (2 papers, 2016 to 2020). A group of at least three distinct histological types of lung cancer, including non-small cell squamous cell carcinoma, adenocarcinoma, and large cell carcinoma. "CTSS proteolytic degradation of nidogen-1, an essential component of the basement membrane and a substrate of CTSS, is strongly associated with non-small cell lung cancer." (PMID 32398133, 2020).
osteosarcoma (2 papers, 2022 to 2023). A usually aggressive malignant bone-forming mesenchymal neoplasm, predominantly affecting adolescents and young adults. "We found that CTSS was also highly expressed in osteosarcoma cells." (PMID 35264209, 2022). "Among them, MAN2B1, P4HA2, ANPEP, BCAT1, CTSS, and DAPK1 were significantly correlated with the prognosis of patients with osteosarcoma." (PMID 37457661, 2023).
plaque psoriasis (2 papers, 2018). "In particular, IL-36γ has been implicated in plaque psoriasis, and Cathepsin S (Cpss), recently shown to activate IL-36γ, was also upregulated in SPF compared to GF skin." (PMID 29378633, 2018). "The clinical efficacy of CTSS inhibitors is currently under investigation in inflammatory disorders including RA, SLE, plaque psoriasis, and, more recently, SS, both in animal disease models and in human clinical trials." (PMID 30038391, 2018).
sarcopenia (2 papers, 2024 to 2025). Progressive decline in muscle mass due to aging which results in decreased functional capacity of muscles. "Notably, CTSS and CTNNB1 were found to be central in the network, suggesting a potential key role in the pathophysiology of sarcopenia." (PMID 38644354, 2024).
skin cancer (2 papers, 2015 to 2024). "Proteins, ASIP, KRT5, CTSS, and TNFSF8, have the potential as diagnostic and therapeutic targets for skin cancers, and validation through future biological experiments is required." (PMID 39003418, 2024). "This multidimensional approach nominates ASIP, KRT5, CTSS, and TNFSF8 as potential diagnostic and therapeutic targets for skin cancers." (PMID 39003418, 2024). "ASIP was colocalized with all three types of skin cancer and STX8, KRT5, GSK3A, CTSS, and TNFSF8 with BCC." (PMID 39003418, 2024).
soft tissue sarcoma (2 papers, 2020 to 2024). A malignant neoplasm arising from muscle tissue, adipose tissue, blood vessels, fibrous tissue, or other supportive tissues excluding the bones. "Compared to non-metastatic patients, the GREM2 and CTSS genes exhibited significantly higher expression levels, while TINAGL1, ACKR1, and HLA-DRB1 showed a tendency to increase in metastatic soft tissue sarcoma (SS); however, these differences were not statistically significant." (PMID 39735532, 2024).
Airway obstruction (1 paper, 2016). Obstruction of conducting airways of the lung. "Also, the cathepsin S/cystatin C ratio (p = 0.02, OR = 0.87) and age (p = 0.001, OR = 3.02) correlated to severe airway obstruction." (PMID 27994288, 2016).
allergic asthma (1 paper, 2013). A asthma with a basis in a pathological type I hypersensitivity reaction. "Whilst it has yet to be reported in human studies, CTSS is elevated in murine models of allergic asthma and CTSS inhibition is prophylactic to ameliorate airway inflammation." (PMID 23483898, 2013).
allergies (1 paper, 2018). "Further, our preliminary in silico analysis predicted RA to attach to a major cleavage site of the endolysosomal enzyme cathepsin S. This, together with the masking of the major T-cell epitope by RA, could substantially minimize its immunogenicity and thereby prevent allergies." (PMID 29371615, 2018).
aneurysmal disease (1 paper, 2012). "Logistic regression analysis of total plasma cathepsin S as independent biomarker of aneurysmal disease." (PMID 22844527, 2012).
aortic valve stenosis (1 paper, 2023). Aortic valve stenosis (AVS) is a condition characterized by narrowing of the heart's aortic valve opening. "Plasma CTSS was identified as exerting the most proteolytic ability on one of the major protein components of high-density lipoproteins, apolipoprotein A-1, in patients with aortic valve stenosis and a rabbit model of aortic valve stenosis." (PMID 37202785, 2023).
arterial diseases (1 paper, 2017). "Their results suggest these parameters could be used as biomarkers for assessing arterial diseases and AAA, highlighting that more advanced cases of AAA would contain higher levels of cathepsin S in the AAA lesions as well as in circulation." (PMID 29379789, 2017).
Atherosclerotic lesion (1 paper, 2023). A lesion associated with atherosclerosis, a multifactorial and multipart progressive disease manifested by the focal development within the arterial wall of lesions, that ranges from the development of a fatty streak, plaque progression, and plaque disruption. "Laboratory and clinical evidence indicates that the SMCs, ECs, and infiltrated macrophages function as major cell sources for the CTSs (CTSS, CTSK, CTSL, and CTSB) in human and animal atherosclerotic lesions." (PMID 37202785, 2023).
cholangitis (1 paper, 2025). An acute or chronic inflammatory process affecting the biliary tract. "Clinically, serum CTSS concentrations are elevated in patients with PBC and show positive correlations with alkaline phosphatase (ALP) and γ-glutamyl transferase (GGT), suggesting a link between CTSS and the burden of cholangitis/fibrosis." (PMID 41153801, 2025).